GPA33 (glycoprotein A33)
Diseases named in the same sentence as GPA33 in open-access papers (continued):
Sharing a sentence is not in itself a finding about the gene and the disease.
cancer (16 papers, 2012 to 2026). A tumor composed of atypical neoplastic, often pleomorphic cells that invade other tissues. "GPA33 and Claudin 18.2 exhibit statistically significant mutually exclusive expression in cancer tissue cores; 36% of cancers are GPA33+/Claudin 18.2-, whilst 22% are GPA33-/Claudin 18.2+." (PMID 41808009, 2026). "A large-scale proteogenomics screen in OAC identified glycoprotein A33 (GPA33) protein as a dominating cancer-specific target." (PMID 41808009, 2026). "We quantified co-immunofluorescence of these antigens with GPA33 and found that GPA33-negative cancer cells displayed high levels of nuclear β-catenin, indicating high WNT activity, and strong expression of the EMT marker LAMC2." (PMID 39472498, 2025). "We grouped cancer cells into GPA33-high and -low clusters and looked for differences in pathway activities through assessment of expression of specific target gene signatures." (PMID 39472498, 2025). "Although the function of the glycoprotein A33 is unclear, it has been recognised as a specific marker of colonic epithelium and cancer." (PMID 35343093, 2022). "The highly restricted expression of GPA33 to the intestinal epithelium and CRC is a hallmark that has sustained the interest in GPA33 as a target for antibody-based cancer therapy." (PMID 26035389, 2015). "These properties all together make GPA33 a good target for cancer treatment." (PMID 41596412, 2026). "Thus, this trimeric IMTX using the scFv against GPA33 as the target domain should be a good strategy to treat cancer, regarding its effectiveness on a monomeric form, and with the enhanced effectiveness of a trimeric design." (PMID 41596412, 2026). "Further study will thus be necessary to determine if GPA33 directed CAR T cells may be cancer specific." (PMID 39472498, 2025). "Therapeutic trials are already underway using GPA33-directed therapies in other cancers, and our finding of EAC-specific expression of this cell surface protein in a significant proportion of patients provides evidence to extend trials to consider patients with EAC." (PMID 38604503, 2024). "Both GPA33 and CSF-1 show promising potential for targeted anti-cancer treatment." (PMID 33671266, 2021). "To test the functionality of GPA33-CAR, we conducted a co-cultivation assay of Jurkat-derived CAR T cells with target cancer cells." (PMID 39472498, 2025). "The limited expression of GPA33 in patient-matched normal tissues provides a compelling basis for further development of this as an EAC biomarker for imaging and cancer detection or development as a therapeutic target." (PMID 38604503, 2024). "On the other hand, the uptake rate of such antigens as GPA33 and CD20 is slow, leading to an increased effective period of radionuclide immobilization on cancer cells." (PMID 26729091, 2015). "Glycoprotein A33 (GPA33) was found to be universally expressed on CSCs and non-CSCs populations using a panel of cancer stem-like cell lines derived from human CRC specimens." (PMID 33240813, 2020). "Notably, proliferation was higher in the GPA33-positive cancer cell population than in GPA33-negative cancer cells, as indicated by Ki67." (PMID 39472498, 2025). "GPA33-negative stem-like cancer cells may undergo EMT and disseminate to distant organs where GPA33 expression is regained at the metastatic site, likely due to differentiation gradients established by microenvironmental cues." (PMID 39472498, 2025). "GPA33-negative cells display an undifferentiated, WNT-active stem-like phenotype, expressing EMT markers and are therefore likely to drive cancer progression upon therapy evasion." (PMID 39472498, 2025).
GPA33 also shares sentences with these, for which no sentence is quoted: infection (4 papers); acute myeloid leukemia (1); adenocarcinoma (1); adenoma (1); breast carcinoma (1); cervical cancer (1); cholangiocarcinoma (1); Colon (1); colorectal tumours (1); kidney cancer (1); lung carcinoma (1); metastatic tumours (1); neuroblastoma (1); oesophageal adenocarcinoma (1); pancreatic cancer (1); Sjögren's syndrome (1); squamous non-small-cell lung cancers (1); ulcerative colitis (1).